ALB (albumin)
Diseases named in the same sentence as ALB in open-access papers (continued):
Sharing a sentence is not in itself a finding about the gene and the disease.
osteoporosis (continued). "CKD-associated osteoporosis is highly prevalent in CKD G5D patients over 50 years old, especially in females with low grip strength and low albumin levels." (PMID 41513977, 2026). "Numerous studies have demonstrated a strong correlation between osteoporosis and nutritional status and inflammation, while albumin and globulin are important references for nutritional status and inflammation, respectively." (PMID 40661684, 2025). "Overall, significant associations were observed between the occurrence of osteoporosis and increased levels of hemoglobin A1c and ALP, as well as decreased levels of hemoglobin, albumin, and prealbumin (all p < 0.05)." (PMID 41480543, 2025). "Logistic regression analyses with gender and age showed that ALB, FPG, HDL-C, and VitD were common risk factors for osteoporosis and H. pylori infection." (PMID 38475712, 2024). "An inverse relationship between serum albumin levels and the prevalence of osteoporosis was observed." (PMID 38731106, 2024). "Studies have demonstrated that the cobalt binding capacity of albumin is diminished in individuals diagnosed with osteoporosis, reflecting oxidative damage and a decline in albumin functionality." (PMID 38883185, 2024). "Albumin, an essential protein in the bloodstream, is significantly correlated with muscle mass and strength in elderly individuals with osteoporosis, suggesting a potential nutritional link." (PMID 38883185, 2024). "The remaining patient (2.63%) was eucalcaemic (defined as serum calcium adjusted for albumin in the range of 2.2 to 2.6 mmol/L) hyperparathyroid with advanced osteoporosis being the indication for operative management." (PMID 38449925, 2024). "The results of the ROC curve analysis demonstrated the ability of the three nutritional assessment tools to predict osteoporosis when combined with age and albumin, respectively." (PMID 37805606, 2023). "ROC curve analysis showed that GNRI in combination with age and albumin had better predictive ability for osteoporosis than PNI and CONUT." (PMID 37805606, 2023). "The results of the ROC curve analysis showed that the GNRI combined with age and albumin had the best ability to predict osteoporosis compared with the PNI and CONUT scores." (PMID 37805606, 2023). "Serum albumin was lower in patients with OSO osteoporosis (3.10 ± 0.79 g/dL) compared with levels among patients without osteoporosis (3.42 ± 0.67 g/dL) (Z = 1.99; p = 0.047)." (PMID 37373124, 2023). "Even though we found that patients in the osteopenia and osteoporosis groups had lower albumin levels than patients in the normal BMD group, lower albumin was not an independent factor of BMD." (PMID 37122165, 2023). "GNRI combined with age and albumin had better predictive ability for osteoporosis than PNI and CONUT scores." (PMID 37805606, 2023). "Patients in the osteopenia and osteoporosis groups presented with lower albumin levels than patients in the normal BMD group (p < 0.05)." (PMID 37122165, 2023). "Improved HL, DDL, education, WC, albumin, Hb, and Hct levels should be considered in preventing hemodialysis patients from developing osteoporosis." (PMID 36501153, 2022). "In line with our findings, another study on rheumatoid arthritis patients during the postmenopausal stage revealed that the serum albumin concentrations were lower in the osteoporosis group than in the non-osteoporosis group." (PMID 36501153, 2022). "For LS BMD, the difference in serum albumin level was significant between osteoporosis and normal groups (P = 0.02)." (PMID 33180791, 2020). "Postmenopausal osteoporosis patients had a significantly lower albumin concentration than the osteopenia group ([40.1 ± 5.4] vs [44.7 ± 4.2] g/L, P < .05)." (PMID 31423643, 2020). "None of the patients with both IBD and CD had any of the major signs or symptoms suggesting malabsorption like amenorrhea, osteoporosis, low albumin, or cholesterol levels." (PMID 31885543, 2019).
osteoporosis (continued). "The variables assessed included demographic data, neutrophil-to-lymphocyte ratio, surgical duration, hospital stay, American Society of Anesthesiologists (ASA) score, cardiac ejection fraction (EF), Charlson Comorbidity Index (CCI), osteoporosis status, and hemoglobin and albumin levels." (PMID 41303773, 2025). "Laboratory parameters, including serum albumin, calcium, phosphate, uric acid, parathyroid hormone (PTH) level, bone turnover markers and lipid profile were explored for potential associations with osteoporosis and fractures." (PMID 40721250, 2025). "Furthermore, studies have also indicated a correlation between low levels of serum albumin and osteoporosis (OR: 4.59, 95% CI: 1.49–14.16, p = 0.025)." (PMID 41480543, 2025). "In conclusion, based on a cross-sectional study, we analyzed the related factors of sarco-osteoporosis, which included age, regular exercise, height, albumin and LMI, and we developed and validated a simple nomogram to predict the risk of SOP for the middle-aged and elderly hospitalized patients." (PMID 38539146, 2024). "When albumin peptide levels are too high or metabolic function is impaired, osteoporosis may result." (PMID 38475712, 2024). "H. pylori may affect osteoporosis through serum albumin, high-density lipoprotein, fasting blood glucose and vitamin D." (PMID 38475712, 2024). "While some studies suggest a potential link between the two, others have not found direct evidence supporting osteoporosis as a causative factor in lowering serum albumin levels." (PMID 38883185, 2024). "The incidence of osteoporosis increased as the albumin levels decreased." (PMID 38475712, 2024). "Moreover, participants with osteoporosis had lower levels of serum albumin, triglycerides, uric acid, AST, ALT, and bilirubin, while exhibiting higher levels of serum total calcium, vitamin D, phosphorus, alkaline phosphatase, total cholesterol, and BUN." (PMID 39170357, 2024). "H. pylori may affect osteoporosis through serum albumin, high-density lipoprotein, fasting blood glucose, and vitamin D. Thus, in the clinic, infection with H. pylori should not be ignored in the management of osteoporosis." (PMID 38475712, 2024). "Additionally, Clinical 6 (red blood cell count), Clinical 9 (alkaline phosphatase), and Clinical 11 (albumin) were also helpful in identifying individuals with osteoporosis, since they were considered as top 10 important features by one or two classifiers." (PMID 35144529, 2022). "Furthermore, GNRI is a more accurate clinical predictor of osteoporosis occurrence than BMI, albumin, and age." (PMID 36523597, 2022). "The subjects with a higher BMI and higher serum albumin levels had lower odds of osteoporosis." (PMID 35684005, 2022). "In addition, serum creatinine, UA, ALB, and serum phosphorus levels of patients with osteopenia and osteoporosis were decreased compared to patients with normal T-scores." (PMID 36337638, 2022). "Hence, in clinical practice, health care providers should be aware of the correction between albumin, Hb, and Hct levels in order to protect against osteoporosis in hemodialysis patients." (PMID 36501153, 2022). "In particular, CBPB reduced the osteoporosis risk within subgroups with dialysis vintage of ≥ 10 years, albumin level of < 3.5 mg/dL, active vitamin D analog use, and no proton pump inhibitor (PPI) use." (PMID 33462371, 2021). "This study aimed to investigate the relationship between albumin-corrected anion gap (ACAG) and lumbar spine bone mineral density (BMD) in a diverse population, assessing how variations in ACAG levels correlate with changes in lumbar spine BMD and the potential implications for osteoporosis risk." (PMID 40007853, 2025). "Our study found that H. pylori may affect osteoporosis through serum albumin, HDL, fasting blood glucose and vitamin D, Which may be involved in the link that H. pylori infection stimulates local and systemic inflammatory factors acting on this aspect of bone conversion." (PMID 38475712, 2024).
osteoporosis (continued). "Besides, in a receiver operating characteristic analysis for predicting osteoporosis, compared with serum albumin, BMI, and age, the GNRI had the largest area under the curve, indicating that the GNRI was a powerful indicator to improve the accuracy of diagnosis." (PMID 35656160, 2022). "There are significant differences in age, height, weight, ALT, ALB, ALP, AST, Cr, UA, BUN, TG, and Hb between male osteoporosis and non- osteoporosis populations (P < .05)." (PMID 40859517, 2025). "Male patients with osteoporosis exhibited significantly higher levels of GGT and HDL, whereas their calcium and albumin levels were significantly lower." (PMID 39046667, 2024). "After adjusting for age, sex, smoking, alcohol consumption, BMI, ALB, Cr, UA, FBG, TG, and HDL, the correlation between GNRI and osteoporosis remained." (PMID 37805606, 2023). "The relationship between albumin levels and BMD and osteoporosis can be explained in several ways." (PMID 40661684, 2025). "Regarding clinical measurements, participants with osteoporosis had lower eGFR, lower serum albumin levels, and higher serum phosphorus and calcium levels compared to those without osteoporosis." (PMID 39922960, 2025). "In our study, the predictability of the GNRI for osteoporosis was stronger compared to albumin and the BMI alone, which were not significant." (PMID 39768664, 2024). "Participants with osteoporosis had significantly higher total cholesterol and HDL levels, whereas participants without osteoporosis had higher diastolic blood pressure, creatinine, uric acid, ALT, triglyceride, and albumin levels." (PMID 39046667, 2024). "Fourthly, the relationship between osteoporosis and reduced serum albumin concentrations remains complex and not fully elucidated in the current literature." (PMID 38883185, 2024). "Here, it was found that the serum albumin level of the normal bone-mass group was higher than that of the low bone-mass and osteoporosis groups and showed a moderate negative correlation in the Spearman test." (PMID 38475712, 2024). "Hemoglobin, albumin, total cholesterol, LDL-C, and TG levels were also significantly higher in subjects with normal BMD, whereas mean fasting glucose level was highest in subjects with osteoporosis." (PMID 36902637, 2023). "The level of serum albumin was lower (p = 0.002), and the levels of bone metabolism markers, including intact PTH (p < 0.001), sALP (p < 0.001), ß-CTX (p = 0.01), and P1NP (p < 0.001), were significantly higher in osteoporosis patients." (PMID 37093441, 2023). "Similar to osteoporosis, the ESRD patients with vascular calcification were older (p < 0.001), were more likely to be on hemodialysis (p = 0.02), had a longer dialysis duration (p < 0.001) and had a reduced level of serum albumin (p < 0.001)." (PMID 37093441, 2023). "With regard to laboratory data, mean serum phosphate levels and Kt/V ratios were higher in the osteoporosis group, whereas serum albumin, serum calcium, and serum intact PTH levels were not significantly different." (PMID 33462371, 2021). "Univariate logistic regression analysis revealed that Hb, TBIL, GGT, and serum albumin were negative predictors, whereas sex, age, omentin-1, and prevalence of DN were positive predictors of the presence of osteoporosis." (PMID 33149724, 2020). "The presence of osteopenia and osteoporosis did not correlate with the duodenal histology findings (Marsh 0 or Marsh 1 and presence/absence of eosinophil infiltration), nor with the presence of the DQ2 or DQ8 alleles, or with the serum level of albumin and triglycerides (data not shown)." (PMID 25430806, 2014). "Within the external dataset, individuals with osteoporosis exhibited significantly lower levels of age, BMI, HDL-C, TC, ALB, TBIL, TG, and TyG compared to those without osteoporosis (P < 0.05)." (PMID 41585803, 2025).
osteoporosis (continued). "It was found that age, SBP, FPG, DBP, ALB, LDL-C, hs-CRP, and OC were positively correlated with osteoporosis, while negative correlations were observed with BMI, LYM, ALB, TP, TG, HDL-C, SCr, UA, and VitD." (PMID 38475712, 2024). "The reduction level of albumin and vitamin OHD was not significant in osteoporosis patient group." (PMID 28702147, 2017).
lymph node metastasis (109 papers, 2012 to 2026). "ALB was identified as an independent risk factor for lymph node metastasis in gastric NE tumor patients." (PMID 39318189, 2024). "PTPRS was associated with serum albumin (P = 0.028), lymph node metastasis (P = 0.038), and the survival time of patients (P = 0.011)." (PMID 35991009, 2022). "They showed that a low level of hemoglobin, albumin, lymphocyte, and platelet was associated with lymph node metastasis, poor tumor differentiation and, high TNM staging." (PMID 34288963, 2021). "Univariate analyses revealed that preoperative serum albumin, type of resection, tumor invasion, lymph node metastasis, and pTNM stage were associated with RLN count (P < 0.05)." (PMID 32838799, 2020). "GNRI was significantly associated with BMI (p < 0.0001), tumor size (p = 0.0473), depth of tumor (p = 0.0071), lymph node metastasis (p = 0.0076), intraoperative blood loss (p = 0.0191), serum albumin levels (p < 0.0001), and CRP levels (p = 0.0019)." (PMID 32754301, 2020). "MVV level was associated with age, BMI, total protein, albumin, tumor size, lymph node metastasis, and tumor stage (P<0.05)." (PMID 28423645, 2017). "A univariate analysis showed that patient age, BMI, total protein, albumin, tumor size, Borrmann type, pathological type, tumor depth, lymph node metastasis, tumor stage, FVC, and MVV were associated with prognosis." (PMID 28423645, 2017). "They found that an elevated preoperative FPR was significantly associated with more advanced tumor invasion, lymph node metastasis and larger tumor size, and it was superior to the levles of fibrinogen, albumin and pre-albumin with regard to independently predicting poor survival in such cases." (PMID 31772657, 2019). "Multivariate Cox regression analysis revealed that age, tumor length, pathological tumor-node-metastasis (pTNM) stage, venous invasion, lymph node metastasis, serum albumin and C-reactive protein levels, and GPS were associated with postoperative survival of these patients." (PMID 27151090, 2016). "Our study implied that younger age, lymph node metastasis, lower pre-operative albumin and higher post-operative bilirubin were significantly associated with early recurrence in patients with curative resection." (PMID 38316853, 2024). "In summary, factors such as HE4, lymph node metastasis, albumin, ALP, and ECOG scores play pivotal roles in influencing the success of debulking surgery for epithelial ovarian cancer." (PMID 39050577, 2024). "Albumin, ALP, ECOG scores, HE4, and lymph node metastasis were identified as key independent risk factors (p < 0.05) affecting the satisfaction level of patients with ovarian cancer undergoing debulking surgery." (PMID 39050577, 2024). "The model equation was as follows: 6.562 − 0.192 × albumin − 2.179 × ALP + 2.027 × ECOG score + 1.536 × HE4 + 1.740 × lymph node metastasis." (PMID 39050577, 2024). "Baseline patient characteristics including gender, BMI, comorbidity, tumor location, albumin concentration, histologic type, preoperative chemoradiation, tumor stage, and lymph node metastasis status were balanced between the two groups." (PMID 38183462, 2024). "Multivariate regression analysis identified albumin levels, ALP, ECOG scores, HE4, and lymph node metastasis as independent risk factors for satisfactory surgical outcomes in patients with ovarian cancer undergoing debulking surgery as (p < 0.05)." (PMID 39050577, 2024). "On univariate analysis, the number of organs involved (p = 0.021), lymph node metastases (p = 0.015), histological subtype (p < 0.001), c.Ca2+ (p < 0.001), albumin (p = 0.004), CRP (p < 0.001) and mGPS (p < 0.001) were predictive of tSACT." (PMID 36207803, 2023). "On univariate analysis, number of organs involved (p = 0.027), lymph node metastases (p = 0.008), albumin (p = 0.001), CRP (p < 0.001) and mGPS (p < 0.001) were predictive of OS." (PMID 36207803, 2023).